NRAS (NRAS proto-oncogene, GTPase)
Diseases named in the same sentence as NRAS in open-access papers (continued):
Sharing a sentence is not in itself a finding about the gene and the disease.
melanoma (continued). "NRAS mutations are most frequently observed in hematological malignancies and are also common in some solid tumors such as melanoma and colon cancer." (PMID 38317235, 2024). "Oncogenic mutations in BRAF, NRAS HRAS genes have been described commonly in melanomas of skin and other sites, however, the same at this site has been conspicuously absent." (PMID 38509523, 2024). "Although the majority of melanomas are characterized by a clonal mutation in either BRAF or NRAS, likely limiting the added clinical value of mFast‐SeqS in patients with melanoma, we demonstrated that ddPCR showed a high correlation with mFast‐SeqS." (PMID 38790134, 2024). "A small-cohort, multi-institutional retrospective investigation indicates that advanced melanoma patients with NRAS mutations respond better to first-line immunotherapy." (PMID 39195270, 2024). "An NF1 mutation is associated with desmoplastic melanomas, while an NRAS mutation is associated with nevoid melanomas." (PMID 38247727, 2024). "RAS mutations typically impact the protein NRAS, most commonly in codon 61 (Q61R and Q61K), and are present in approximately 30% of melanomas." (PMID 39126091, 2024). "A recent retrospective, multi-center study evaluated the clinical course of patients with NRAS mutated stage IV melanoma treated with MEKi and at least one prior line of treatment." (PMID 38263136, 2024). "Our study confirms the co-occurrence of BRAF and NRAS mutations in melanoma and emphasizes the metastatic potential of a melanoma tumor that displays both of the mentioned mutations." (PMID 38396984, 2024). "The presence of an NRAS mutation has historically been correlated with poorer overall survival in patients with advanced melanoma, but its prognostic impact in the modern treatment era is less clear." (PMID 38611025, 2024). "The immunogenicity of NRAS mutations in patients with melanoma was demonstrated by the detection of T cell responses against the NRASQ61K neoantigen." (PMID 39576860, 2024). "For example, KRAS mutants dominate the Ras mutational burden in pancreatic cancer and NSCLC, whereas NRAS is most mutated in melanoma and acute myeloid leukaemia." (PMID 39372214, 2024). "The discovery of activating NRAS mutations in melanoma in the mid-1980s and the subsequent identification of BRAF mutations in 2002 have been significant milestones in understanding melanoma’s molecular pathology." (PMID 38474231, 2024). "A similar observation was made with MelJuso cells representing the second-most common genetic subtype of human melanoma bearing an oncogenic NRAS mutation." (PMID 39436655, 2024). "Recently, P2X7 activation was associated with improved therapy responses in NRAS-mutant melanoma, presumably by reducing the rise in resistant cells." (PMID 39001489, 2024). "An overwhelming proportion of melanomas harbor hotspot mutations in either the BRAF or NRAS oncogenes—over 50% and approximately 20–25% of melanomas, respectively." (PMID 38732242, 2024). "Second-line treatments for melanomas with NRAS mutations include inhibiting the MAPK signaling pathway, MEK, or a combination with other drugs." (PMID 38462618, 2024). "UV exposure in melanoma development is highly implicated by mutations in the NRAS and BRAF genes and influenced by the amount of eumelanin produced in the skin." (PMID 38534742, 2024). "In a study by Zhou L, the presence of NRAS mutation was associated with a poorer response and worse prognosis in patients with advanced melanoma treated with iPD-1." (PMID 39410017, 2024). "Our study also highlights the extent of spare signaling capacity in the ERK pathway in melanoma cells with BRAF or NRAS mutations." (PMID 39436655, 2024). "The combined use of a phosphoinositide-dependent kinase 1 (PDPK1) inhibitor (GSK2334470) and a MEK inhibitor (trametinib) suppressed NRAS-mutant xenograft growth and induced GSDME-associated pyroptosis in NRAS-mutant melanoma model mice." (PMID 38336727, 2024).
melanoma (continued). "Instead, eIF4F activity is essential for controlling ERK MAPK signaling flux in treatment-naïve human melanoma cells bearing NRAS and BRAF oncogenic mutations." (PMID 39436655, 2024). "RAF1 and BRAF mutations had a higher prevalence in HRASmt melanoma and UC, respectively, whereas NRAS mutations were more prevalent in HRASwt melanoma." (PMID 38672653, 2024). "Further, KRAS is mutated in pancreatic and lung cancer, NRAS in melanoma and HRAS in oral and skin SCC." (PMID 38963974, 2024). "Among the melanoma samples included in our study, 11 (50%) had NRAS G12/G13 mutations (mutational load ranging from 0.4% to 2.5%)." (PMID 38396984, 2024). "Patients with both BRAF and NRAS mutations have a poorer prognosis compared to those bearing either NRAS wild-type or BRAF-mutant melanoma." (PMID 38396984, 2024). "Thirteen (19%) and 20 (30%) patients had BRAF V600 mutations and NRAS-mutant melanoma, respectively." (PMID 38956747, 2024). "Our results indicate that targeting T-RECS represents an untapped therapeutic opportunity to treat NRAS-mutated/MAPK-driven melanoma." (PMID 38383439, 2024). "Activating mutations in either of the three RAS isoforms (HRAS, KRAS, or NRAS) are found in nearly 20% of all human tumors with NRAS mutated in ~25% of melanomas." (PMID 39379700, 2024). "Altogether, ASO-mediated T-RECS inhibition represents an unprecedented therapeutic opportunity to treat NRAS-/BRAF-mutated melanoma." (PMID 38383439, 2024). "Encorafenib (BRAF inhibitor) and binimetinib (MEK inhibitor) have demonstrated efficacy in patients with NRAS-mutated melanoma." (PMID 38399429, 2024). "Of all RAS isoforms (HRAS, KRAS, and NRAS in humans), the most common mutation in melanomas occurs in the NRAS gene, while in other types of human cancers, mutations are more frequent in the KRAS gene." (PMID 39770908, 2024). "Identification of the essential role of the oncogenic BRAF and NRAS mutations activating ERK signaling for melanoma development and survival has led to the development of pharmacological BRAF and MEK inhibitors." (PMID 39436655, 2024). "The second most commonly reported MAPK pathway aberration in melanoma is mutated NRAS, occurring in ~15–30% of internationally published cases." (PMID 38183457, 2024). "Congenital nevi can be associated with nevus-associated melanoma and are also usually caused by an NRAS mutation." (PMID 39335684, 2024). "As already reported, melanoma patients harboring pTERT mutations in combination with BRAF/NRAS mutations have a significantly shorter PFS than patients without this combination." (PMID 38548846, 2024). "The current landscape of melanoma research, with its exploration of NRAS, TMB, BRAF, EGFR, c-KIT, and other mutations, offers a promising trajectory for future endeavors in understanding and combatting this disease." (PMID 38534309, 2024). "Differential methylation in NRAS mutated melanomas, especially promoter hypermethylation of p16, was previously observed." (PMID 38790134, 2024). "We reasoned that the different ways in which panRAF and MEK inhibitors combine in NRAS vs. BRAF mutant melanomas likely originate from the distinct pathway rewiring caused by these oncogenic mutations." (PMID 39199684, 2024). "NRAS-mutated melanomas and NF1-mutated melanomas are both UV-driven but they are different phenotypically and biologically." (PMID 38247727, 2024). "Since activating mutations in RAS oncogenes are found in a third of all human cancers and NRAS mutations are found in 15–20% of melanomas, we decided to study this as well." (PMID 39061208, 2024). "In the clinical setting, it is recommended to initially test for BRAF and NRAS mutations in acral and mucosal melanomas." (PMID 38474231, 2024). "Melanomas with mutations in NRAS, the second most prevalent mutated proto-oncogene in melanoma, are characteristically more aggressive and susceptible to developing resistance to treatment when compared to BRAF mutants." (PMID 38732242, 2024).
melanoma (continued). "While our study focuses on the role of T-RECS in NRAS-mutated/MAPK-driven melanoma cell survival, it likely has broader functions in other types of melanomas and cancers, as well as in pre- and non-malignant tissues." (PMID 38383439, 2024). "Since patients with NRAS-mutated CM have a poor prognosis and limited treatment options, we aimed at deciphering tumor-intrinsic promotors of NRAS-mutated melanoma for metastasis to the lungs and the liver." (PMID 37179302, 2023). "Melanoma is the major cancer type caused by NRAS mutation; therefore, we carried out NRAS depletion experiments in SK-MEL-2 cells." (PMID 37083947, 2023). "NRAS (N-Ras) protein is an intrinsic GTPase associated with the progression of glioblastoma multiforme and melanoma, by regulating cell migration, growth, and angiogenesis." (PMID 38107644, 2023). "In conclusion, this phase I trial established the RP2D of HL-085 as 12 mg BID in patients with advanced melanoma with NRAS mutations." (PMID 36600247, 2023). "This study demonstrates that tumor-intrinsic properties influencing the metastatic pattern of NRAS mutated melanoma are strongly affected by hepatic passaging and the hematogenous route tumor cells take." (PMID 37179302, 2023). "OKI-179 is currently being investigated with the MEK inhibitor binimetinib in patients with NRAS-mutated melanoma in the phase 2 Nautilus trial." (PMID 38201519, 2023). "All of these alterations (except NRAS mutations which only occurred within melanoma brain metastases) occurred across multiple cancer types." (PMID 36915611, 2023). "NRAS mutations found in 25% of melanoma cases have been associated with lower median overall survival and high aggressiveness with lack of efficient targeted therapies and also emerging resistance to existing treatments options." (PMID 37483495, 2023). "In the NRas/Ink4a model of melanoma, loss of CXCR2 expression during tumorigenesis also resulted in reduced tumor growth, without a significant reduction in tumor incidence." (PMID 37270599, 2023). "More than 80% of NRAS mutated melanoma carry the substitution of glutamine with arginine, lysine, or leucine at position p.61 (NRASQ61R/K/L)." (PMID 36982192, 2023). "Oncogenic NRAS mutations occur in several cancer types, notably melanoma, acute myeloid leukemia, colon and thyroid cancers, and other hematologic malignancies." (PMID 37834310, 2023). "For patients with melanoma harboring NRAS mutations, a particular genetic melanoma subtype, treatment options with regard to targeted therapy are still very limited." (PMID 38067230, 2023). "The peaks corresponding to m/z 944.4, 1825.9, and 2169 were identified as the main discriminating factors for BRAF mutated versus NRAS mutated malignant melanoma (MM)." (PMID 36982192, 2023). "We established two melanoma cell lines with different NRAS mutational backgrounds resistant to GANT-61." (PMID 37239024, 2023). "Activating mutations in the NRAS gene have been identified in melanoma and can lead to the constant activation of the RAS-RAF-MEK-ERK-MAPK pathway." (PMID 37504268, 2023). "Classification models showed molecular differences between BRAF and NRAS mutated melanoma, and identification of both was possible with an accuracy of 87–89% and 76–79%, depending on the respective classification method applied." (PMID 36982192, 2023). "The overall response to binimetinib monotherapy in NRAS-mutated melanoma was 15%, making combination treatment a promising strategy for the treatment of NRAS-mutated melanoma." (PMID 38067230, 2023).
melanoma (continued). "Among them, genetic alterations leading to abnormal activations of the Ras signaling pathway represent the most common oncogenic driver mutations, particularly BRAF and NRAS mutations, which occur in approximately 50% and 15% of melanomas, respectively." (PMID 37404751, 2023). "Somatic NF1 mutations often co-occur with other genetic alterations, particularly BRAF and NRAS mutations, which are common in melanoma." (PMID 37504268, 2023). "This distinct glycolytic phenotype in BRAF-mutated melanomas is triggered by mutations in NRAS and BRAF." (PMID 37627054, 2023). "CRAF was reported as the primary RAS effector signaling through ERK specifically in melanoma cells harboring NRAS mutations." (PMID 38111008, 2023). "Overall, these data indicate the promising potential of HL-085 as a novel therapeutic agent for patients with advanced melanoma with NRAS mutations." (PMID 36600247, 2023). "BRAF-mutated melanomas have a significantly better prognosis than NRAS-mutated or BRAF-NRAS-co-mutated melanomas." (PMID 37373134, 2023). "BRAFwt/NRASwt patients have decreased melanoma-specific survival compared to those with NRAS or BRAF mutations." (PMID 36909026, 2023). "In a pooled analysis study of four Asian clinical trials on anti‐PD‐1 monotherapy, advanced melanoma with NRAS mutations had lower response rate and poorer prognosis, especially in acral and mucosal subtypes." (PMID 37403699, 2023). "We chose to model BRAFV600E and NRAS-mutant tumors because these mutations are dominant in a substantial fraction of cutaneous primary melanomas and are well represented in preclinical models." (PMID 37043573, 2023). "Among these mutations, BRAF and NRAS are two of the most common, but also mutually exclusively mutated, oncogenes recognised in melanoma." (PMID 37627054, 2023). "A common mutation found in melanoma patients is BRAFV600E whereas tumours bearing NRAS mutations are less frequent but more aggressive and associated with shorter survival." (PMID 37608347, 2023). "Ten melanomas carried mutations in the Q61 position of NRAS (5 Q61K, 2 Q61L, 2Q61R and 1 Q61H) and one sample carried the rare, but likely, oncogenic substitution A59T." (PMID 36765773, 2023). "The NRAS mutated subtype, which accounts for a quarter of all melanoma cases, lacks such a targeted approach but ongoing clinical trials are assessing the effects of combined MEK and CDK4/6 inhibitors (NCT01781572; NCT02065063)." (PMID 37420093, 2023). "These mutations result in activation of the NRAS protein and can lead to uncontrolled cell growth and proliferation, contributing to the development and progression of melanoma." (PMID 37504268, 2023). "In a Phase Ib upgrade/expansion study, LXH254 was evaluated in conjunction with trametinib among patients grappling with advanced/metastatic non-small cell lung cancer harboring KRAS or BRAF mutations and NRAS-mutated melanoma (NCT02974725)." (PMID 38111008, 2023). "The NRAS gene mutations are mostly related to hematopoietic cancers, bladder cancers, and melanomas." (PMID 37361584, 2023). "The second most common cause of aberrant activation of the MAPK pathway in cutaneous melanoma is represented by NRAS-activating mutations (15–30% of melanomas)." (PMID 36978794, 2023). "We investigated the performance of several tissue classifiers, with two types of cross-validation in order to identify proteomic differences characterizing BRAF and NRAS mutated melanoma." (PMID 36982192, 2023). "OKI-179 is currently being investigated in combination with the MEK inhibitor binimetinib in patients with NRAS-mutated melanoma." (PMID 38201519, 2023). "Numerous efforts are underway to target melanomas with NRAS mutations, NF-1 LOF mutations, and other genetic alterations leading to activation of the MAP kinase pathway." (PMID 37370834, 2023).
melanoma (continued). "The BRAF mutation affects serine-threonine kinase BRAF and is found in ~40–60% of melanoma, while the NRAS mutation affects the RAS protein responsible for activating the signaling pathways that control cell proliferation, differentiation and survival." (PMID 37627116, 2023). "Hotspot mutations in the NRAS gene are causative genetic events associated with the development of melanoma." (PMID 36765834, 2023). "Currently, a phase II trial evaluating the efficacy of pan-RAF inhibitor naporafenib combined with ribociclib in patients with unresectable or metastatic NRAS-mutated melanoma is in progress (NCT04417621)." (PMID 37370834, 2023). "KRAS mutations were more prevalent in NSCLC (p<0.01) and NRAS mutations in thyroid and melanoma (both p<0.05)." (PMID 37503077, 2023). "This is the case, for instance, in NRAS-mutated melanoma, in which RAF1 and BRAF compensate for each other, and ARAF compensates for the loss of both other isoforms in a mechanism that is still ERK-dependent." (PMID 37020037, 2023). "Similar to leukemia, NRAS palmitoylation is required for pro‐tumorigenic NRAS signaling in melanoma, which often carries NRAS activating mutations." (PMID 36018061, 2023). "Approximately 9–21.9% acral melanomas have NRAS mutations and 11–23% acral melanomas harbor NF1 mutations." (PMID 37239381, 2023). "One study evaluated the use of the MEK inhibitor binimetinib in patients with NRAS-mutated melanoma." (PMID 37504268, 2023). "In melanoma, NRAS mutations occur in 15 to 23.15% of tumors and are usually mutually exclusive with BRAF and KIT36." (PMID 36658200, 2023). "The natural history of BRAF and NRAS mutant melanoma suggests an increased risk of progression and increased frequency of metastatic disease, including an increased frequency of brain metastases." (PMID 37444637, 2023). "In melanoma and other types of cancer, activating mutations in NRAS and BRAF can constitutively auto-activate the kinases without the requirement of ligand mediated activation, causing hyperactivation of the pathway." (PMID 37235843, 2023). "Given that 15–20% of activating NRAS mutations are found among melanoma patients and lack therapy options outside of checkpoint inhibition, our investigations were focused on NRAS-mutant melanomas." (PMID 36765834, 2023). "The synergistic effect of PDPK1 deletion and MEKi is further validated in a melanoma cell line with the NRAS mutation using pharmacological and molecular methods." (PMID 37427373, 2023). "TCRs cloned from these patients were associated with high potency, as measured by the ability to lyse HLA-A*01 + -positive melanoma cell lines that naturally harbor NRAS mutations." (PMID 37475035, 2023). "ERK5 activation has also been linked to PDGFR signalling in NRAS mutant melanoma treated with MEK and ERK1/2 inhibitors." (PMID 37420093, 2023). "In contrast, WT31 melanoma is driven by a NRAS mutation resembling a cohort of patients with unmet clinical need, even colonizes the liver after intravenous (i.v.)injection and therefore better reflects the broader metastatic pattern of human patients." (PMID 37179302, 2023). "The HL-085 showed acceptable tolerability and substantial clinical activity in patients with advanced melanoma harboring NRAS mutations." (PMID 36600247, 2023). "Activating mutations in the oncogenes BRAF and NRAS are the most studied mutations in malignant melanoma." (PMID 38201531, 2023). "Mutations in the NRAS gene are found in 15–20% of melanomas, while mutations in the NF1 gene (neurofibromin-1) are found in 15% of melanomas." (PMID 37504268, 2023). "NRAS-mutated patients with advanced melanoma at the time of diagnosis have a significantly shorter overall survival (15.5 months vs. 23.5 months)." (PMID 37370834, 2023). "(ρ = 0.494 vs. 0.549) This is significant because NRAS mutations are present in 15–30% of melanoma cases and have been linked to drug resistance mechanisms." (PMID 37235843, 2023).